CHAC2 (ChaC glutathione specific gamma-glutamylcyclotransferase 2)
Description:
Catalyzes the cleavage of glutathione into 5-oxo-L-proline and a Cys-Gly dipeptide. Acts specifically on glutathione, but not on other gamma-glutamyl peptides.
Synonyms: GCG1
Tractability: PROTAC: ubiquitination databases record sites on it.
Gene: Protein-coding gene on chromosome 2 (53,767,804 to 53,775,196, forward strand). Ensembl gene ENSG00000143942.
Subcellular location: Cytoplasm, cytosol
Subcellular location (Human Protein Atlas): Cytosol
Pathways (Reactome):
Metabolism: Glutathione synthesis and recycling
Gene Ontology:
Molecular function: glutathione specific gamma-glutamylcyclotransferase activity
Biological process: glutathione metabolic process; glutathione catabolic process
Cellular component: cytosol
Genetic constraint (gnomAD): Loss-of-function variants: 18 observed, 15.77 expected, observed/expected ratio (o/e) 1.14, 90% interval 0.79 to 1.67. The upper end of that interval is the gene's LOEUF score, 1.67, which puts it in group 6 of 6, group 1 being the genes least tolerant of losing a copy. Missense variants: 248 observed, 213.24 expected, observed/expected ratio (o/e) 1.16, 90% interval 1.05 to 1.29. Synonymous variants: 86 observed, 76.99 expected, observed/expected ratio (o/e) 1.12, 90% interval 0.94 to 1.34.
Homologues: Orthologues: chimpanzee CHAC2 (100% identical), macaque CHAC2 (99% identical), dog CHAC2 (95% identical), rabbit CHAC2 (95% identical), pig CHAC2 (92% identical), mouse Chac2 (91% identical), guinea pig CHAC2 (89% identical), tropical clawed frog chac2 (88% identical), rat Chac2 (73% identical), zebrafish chac2 (68% identical), Drosophila melanogaster CG2540 (48% identical). Paralogues in human: CHAC1 (49% identical).
Diseases named in the same sentence as CHAC2 in open-access papers:
CHAC2 is named in the same sentence as 18 diseases in open-access papers, as found by Europe PMC text mining. Sharing a sentence is not in itself a finding about the gene and the disease. The quoted sentences say what the papers report.
colorectal cancer (7 papers, 2017 to 2025). A primary or metastatic malignant neoplasm that affects the colon or rectum. "High CHAC2 levels are associated with a higher 3-year survival rate in gastric and colorectal cancer patients." (PMID 41488051, 2025). "In gastric and colorectal cancer, high CHAC2 expression leads to reduced glutathione, elevated intracellular Ca2+ and increased ROS, resulting in inhibited tumor growth, proliferation and migration." (PMID 41488051, 2025). "For example, ChaC2 is downregulated in gastric and colorectal cancer, and the overexpression of ChaC2 has been shown to inhibit cell proliferation." (PMID 31878259, 2019). "In colorectal cancer, high CHAC2 expression was also correlated with XBP-1s, active caspase-3 or Beclin 1 high expression with a correlation coefficient of 0.526 (P<0.001), 0.319 (P<0.001) and 0.433 (P<0.001), respectively." (PMID 28837156, 2017). "Through massive expression profiling we identified CHAC2 as a frequently downregulated gene in gastric and colorectal cancers." (PMID 28837156, 2017). "In colorectal cancer patients, CHAC2 expression was significantly correlated with lymph node metastasis (P<0.001), distant metastasis (P=0.017) and TNM stages (P<0.001)." (PMID 28837156, 2017). "In this study, we checked the expression of CHAC2 in gastric and colorectal cancer cell lines and primary tissues." (PMID 28837156, 2017). "In colorectal cancer patients, the CHAC2 expression (P=0.002), histopathological grading (P=0.013) and distant metastasis (P=0.05) were significantly associated with overall survival rates." (PMID 28837156, 2017). "We evaluated the CHAC2 protein expression in primary gastric and colorectal cancer tissues by immunohistochemistry (IHC) and western blot." (PMID 28837156, 2017). "We searched for candidate TSGs in digestive tumors through massive expression profiling, and found that CHAC2 was a frequently downregulated gene in gastric and colorectal cancers." (PMID 28837156, 2017). "Colony formation assays showed that ectopic CHAC2 expression significantly suppressed the colony formation efficiency of gastric and colorectal cancer cells (P<0.01)." (PMID 28837156, 2017). "Firstly, we tested the CHAC2 expression in three gastric cancer cell lines and eight colorectal cancer cell lines." (PMID 28837156, 2017). "In conclusion, this study provides the first evidence that CHAC2 was downregulated and degraded by ubiquitin-proteasome pathway in gastric and colorectal cancers." (PMID 28837156, 2017). "Kaplan–Meier survival indicated that the cumulative survival rate of patients with high CHAC2 expression was significantly higher than those with low CHAC2 expression in both gastric (P<0.001) and colorectal cancer (P=0.001) cases." (PMID 28837156, 2017). "Similar results were found in transwell migration assays, CHAC2 expression led to significant suppression of gastric and colorectal cancer cell migration." (PMID 28837156, 2017). "So in this study, we investigated the regulation mechanism of CHAC2 expression and explored its functions and signaling pathway in the development of gastric and colorectal cancers." (PMID 28837156, 2017). "Similarly, studies in gastric and colorectal cancers have demonstrated that CHAC2 overexpression significantly enhances tumor cell apoptosis, contributing to improved patient survival outcomes." (PMID 39854306, 2025). "Despite little being known about these enzymes in cancer, the CHAC2 isoform has been classified as a tumor suppressor gene in gastric and colorectal cancer studies, correlating CHAC2 downregulation with more aggressive cancer phenotypes and its activation with cancer cells poor survival." (PMID 32882966, 2020). "A better understanding of the molecular mechanisms of CHAC2 in gastrointestinal cancer development may lead to a more effective management of gastric and colorectal cancer patients with the low expression of CHAC2." (PMID 28837156, 2017).
colorectal cancer (continued). "So in gastric and colorectal cancer CHAC2 acted as a tumor suppressor and might have therapeutic implication for patients." (PMID 28837156, 2017). "Moreover, cell viability assays revealed that ectopic CHAC2 expression significantly suppressed the cell proliferation of gastric and colorectal cancer cells (P<0.01), especially after 5-FU treatment (P<0.01)." (PMID 28837156, 2017). "In both gastric and colorectal cancer cases, CHAC2 was found to be frequently downregulated." (PMID 28837156, 2017). "In contrast, CHAC2 was silenced or just low expressed in gastric and colorectal cancer tissues." (PMID 28837156, 2017). "And the CHAC2 expression (HR:0.380; 95% CI: 0.202–0.711; P=0.003) and histopathological grading (HR:1.428; 95% CI: 1.042–1.957; P=0.027) were proved to be independent prognostic factors for survival in colorectal cancer." (PMID 28837156, 2017). "CHAC2 may act as a tumor suppressor in gastric and colorectal cancer." (PMID 36250026, 2022). "CHAC2, a member of the glutathione degrading enzyme family has been shown to suppress gastric and colorectal cancer progression, however, the expression of CHAC2 in breast cancer has not been reported." (PMID 36568153, 2022). "CHAC2 expressed higher in paired non-tumor tissues compared with tumor tissues in 81.25% (13/16) gastric and 87.5% (14/16) colorectal cancer cases, respectively." (PMID 28837156, 2017).
breast carcinoma (3 papers, 2019 to 2025). "The survival plots obtained from Km plotter indicated that high CHAC2 expression correlated significantly with shorter survival indicating that elevated CHAC2 expression negatively associated with the prognosis of breast cancer patients." (PMID 36568153, 2022). "Based on the results of the present study, we showed that CHAC2 is highly expressed in breast cancer and seems to be associated with node metastasis, and stage of breast cancer through various databases." (PMID 36568153, 2022). "The results showed that CHAC2 levels were high in breast cancer patients and elevated CHAC2 was associated with low overall survival." (PMID 36568153, 2022). "We associate the GSH degradation pathway mediated by ChaC2 with breast cancer proliferation and suggest a GSH degradation reaction mechanism." (PMID 31878259, 2019). "In addition, the ChaC2 level in breast cancer tissue was markedly associated with breast cancer survival." (PMID 31878259, 2019). "Therefore, considering the totality of the evidence reported in this study, it is clear that high CHAC2 expression associates with more progressive disease suggesting a novel therapeutic target for breast cancer as well as a biomarker for the aggressiveness of the breast tumor." (PMID 36568153, 2022). "However, the expression of CHAC2 in breast cancer and its association with the prognosis of breast cancer is unknown." (PMID 36568153, 2022). "Kaplan-Meier plotter analysis established the prognostic signifcance of CHAC2 expression in breast cancer." (PMID 36568153, 2022). "We did an analysis of CHAC2 expression in breast cancer patients from various online tools like UALCAN, GEPIA2, GENT2, TIMER2, and bcGenExminer v4.8." (PMID 36568153, 2022). "The relationship between CHAC2 mRNA expression and clinicopathological features of breast cancer from bc-GenExMiner v4.8 database." (PMID 36568153, 2022). "Further online databases (UALCAN, UCSCxena, Enrichr, GEPIA2, and GeneMANIA) deciphered CHAC2 expression in breast cancer through gene ontology studies, interaction, and correlation analysis." (PMID 36568153, 2022). "Taken together, our study explored the CHAC2 expression in breast cancer datasets and aimed to establish its clinical significance in breast cancer." (PMID 36568153, 2022). "Based on these finding, we became interested in the biological effects of ChaC2 on breast cancer cell lines and related mechanisms." (PMID 31878259, 2019). "From cellular experiments, we found that the overexpression of ChaC2 in the MCF-7 breast cancer cell line (an invasive ductal carcinoma) induced cell proliferation." (PMID 31878259, 2019). "In summary, our data firstly revealed that overexpression of ChaC2 unfavorably influences the survival of breast cancer patients due to its capacity of promoting cancer cell proliferation and modulating the antioxidant system." (PMID 31878259, 2019). "Taken together, the ChaC2 mutant’s data suggest that ChaC2 promotes breast cancer cell proliferation, while its active site mutants reduce this effect." (PMID 31878259, 2019). "The results showed a significant overexpression of ChaC2 in this breast cancer cell line and confirmed that the ChaC2 mutants had similar expression levels as ChaC2." (PMID 31878259, 2019). "As such, the GSH degradation activity of ChaC2 was shown to regulate the growth of MCF-7 breast cancer cell lines." (PMID 31878259, 2019). "The result of immune filtration analysis shows that CHAC2 expression may be involved in the regulation of immune cells in breast cancer." (PMID 36568153, 2022). "Taken together, the results of the present study show that like its paralog CHAC1, CHAC2 may also be an important biomarker and could have a potential therapeutic implication in breast cancer." (PMID 36568153, 2022).
breast carcinoma (continued). "Our study warrants further preclinical research with various in vitro and in vivo models to ascertain the molecular mechanisms that regulates CHAC2 expression which may be beneficial in breast cancer diagnosis and treatment." (PMID 36568153, 2022). "The different databases to demonstrate the CHAC2 expression in breast cancer." (PMID 36568153, 2022). "This paves a way for future therapies targeting CHAC2 in breast cancer." (PMID 36568153, 2022). "In addition, we found a close relationship between ChaC2 function and breast cancer from our cell proliferation assay results and previously published breast cancer databases." (PMID 31878259, 2019). "When we analyzed the ChaC2 gene expression in breast cancer tissues from the online clinical database Oncomine, the TCGA, Turashvili Breast, and Karnoub Breast database showed that the transcriptional level of ChaC2 in invasive ductal breast carcinoma was significantly higher than in normal cells." (PMID 31878259, 2019). "From the correlation analysis, it can therefore be inferred that both CHAC2 and TTK may be potential candidate for future therapeutic targets in breast cancer." (PMID 36568153, 2022). "We also found that overexpression of ChaC2, but not mutants that inhibit activity of ChaC2, significantly promoted breast cancer cell proliferation, suggesting that the GSH degradation by ChaC2 affects the growth of breast cancer cells." (PMID 31878259, 2019).
gastric cancer (3 papers, 2017 to 2022). A primary or metastatic malignant neoplasm involving the stomach. "Previously, CHAC2 has been shown to behave as a tumor suppressor in gastric cancer cells transfected with CHAC2 led to enhanced ROS levels, mitochondrial apoptosis, and autophagy through the UPR pathway." (PMID 36568153, 2022). "In gastric cancer, high CHAC2 expression was correlated with XBP-1s, active caspase-3 or Beclin 1 high expression with a correlation coefficient of 0.305 (P=0.002), 0.607 (P<0.001) and 0.591 (P<0.001), respectively." (PMID 28837156, 2017). "Using univariate analysis, CHAC2 expression (P<0.001), the depth of invasion (P<0.001), lymph node metastasis (P=0.003), distant metastasis (P<0.001) and TNM stages (P<0.001) were significantly associated with overall survival rates in gastric cancer patients." (PMID 28837156, 2017). "Recent studies have shown that the overexpression of ChaC2 decreases the GSH levels in yeast cells and gastric cancer cells." (PMID 31878259, 2019). "CHAC2 expression was significantly correlated with histopathological grading (P=0.002), depth of invasion (P=0.039), lymph node metastasis (P=0.017) and TNM stages (P=0.011) in gastric cancer patients." (PMID 28837156, 2017).
B cell lymphoma (1 paper, 2024). "Collectively, our data indicate that CHAC2 is required for stemness in LMP1-expressing cells, and that targeting CHAC2 and LSD1 can be effective approaches for suppressing the stemness of EBV-positive B cell lymphoma cells." (PMID 38514636, 2024).
Breast Invasive Carcinoma (1 paper, 2022). "We then selected “Breast Invasive Carcinoma” and analyzed the correlation of various immune cells with CHAC2 expression." (PMID 36568153, 2022).
breast tumor (1 paper, 2022). "Unsurprisingly, the overall CHAC2 expression enhanced with the node metastasis and stage of the breast tumor indicating that high CHAC2 expression correlated with increasing tumor stage and node metastasis." (PMID 36568153, 2022). "We found high expression of CHAC2 in breast tumor samples and in aggressive subtypes like HER and TNBC compared to luminal subtypes." (PMID 36568153, 2022). "In summary, we found significantly high CHAC2 expression (p-value <0.0001) in breast tumor cases compared to their normal counterparts." (PMID 36568153, 2022).
gastric tumor (1 paper, 2023). "Among autophagy genes in the Reactome database, PRMT1 was negatively correlated with genes such as ATG9A, DYNC1H1, EPAS1, PINK1, TSC1, TUBB6, and ULK1 in gastric tumor tissues (STAD-TCGA) and positively correlated with HMMR, ESCO2, CHAC2, and NUDT6 (STAD-TCGA)." (PMID 37564212, 2023).
interstitial cystitis (1 paper, 2024). A rare chronic debilitating urogenital disease characterized by urinary frequency, urgency, and pelvic pain. "Seven hub genes (SPTBN1, PSME4, CHAC2, ERLEC1, ASB3, STAT5A, and STAT3) were identified as differentially expressed between interstitial cystitis patients and healthy individuals, representing potential therapeutic targets." (PMID 39399486, 2024).
invasive ductal carcinoma (1 paper, 2019). "As such, we examined the effects of ChaC2 and ChaC2 active-site mutants (ChaC2 E74Q and ChaC2 E83Q) overexpressed in invasive ductal breast carcinoma MCF-7 cell lines on cell growth by MTT assays and colony-forming assays." (PMID 31878259, 2019). "Interestingly, the clinical database demonstrate that the ChaC2 level is significantly high in invasive ductal breast carcinoma." (PMID 31878259, 2019).